MIR4638 (microRNA 4638)
Synonyms: hsa-mir-4638; mir-4638
Gene: MicroRNA gene on chromosome 5 (181,222,566 to 181,222,633, reverse strand). Ensembl gene ENSG00000264732.
Homologues: Orthologues: chimpanzee MIR4638 (100% identical).